MIR4486 (microRNA 4486)
Synonyms: hsa-mir-4486
Gene: MicroRNA gene on chromosome 11 (19,575,310 to 19,575,372, forward strand). Ensembl gene ENSG00000265210.
Homologues: Orthologues: chimpanzee MIR4486 (100% identical).